ILK (integrin linked kinase)
Diseases named in the same sentence as ILK in open-access papers (continued):
Sharing a sentence is not in itself a finding about the gene and the disease.
tumor (continued). "As one of the key molecules linking important signaling pathways inside and outside cells, ILK plays a stellar role in the study of skeletal muscle proliferation and tumor therapy." (PMID 26788505, 2015). "ILK plays a very important role in myocardial regeneration, angiogenesis and invasion and metastasis of tumor cells, and matrix adhesion and signal transduction." (PMID 26788505, 2015). "The tumor-promoting effects of ILK, in part, is attributable to its ability to phosphorylate Ser473-Akt and GSK3β, as well as to induce the expression of the oncogenic transcription/translation factor Y-box binding protein 1 (YB-1)." (PMID 25821081, 2015). "We therefore conclude that the interdependence between PINCH1 and ILK is strongly influenced by tumor and tissue type." (PMID 26460618, 2015). "More specifically, they showed that ILK inhibition in human tumour cells results in MST1 and LATS1 activation with concomitant inactivation of YAP/TAZ activities." (PMID 25097725, 2014). "HSP90 can maintain the tumor-like character of rheumatoid synovial cells by stabilizing ILK, ERK, and AKT." (PMID 25398317, 2014). "Increased ILK expression correlates strongly with OSCC tumor invasion, higher tumor grade, advanced clinical stage, positive lymph node status and increased risk of recurrence." (PMID 24466237, 2014). "Previously, we identified several tumor-suppressive miRNAs that are repressed in c-Src–transformed cells: miR-99a targets mTOR to suppress tumor progression, and miR-542-3p targets ILK to suppress tumor malignancy." (PMID 24244675, 2013). "Overexpression of ILK in tumor cells has been found to result in anchorage-independent cell growth, cell cycle progression and tumorigenicity." (PMID 23599801, 2013). "SPARC in tumor tissues can alter the function of stroma and tumor cells and activate downstream pathways, such as ILK, FAK, and MAPK, especially the expression of relevant factors of angiogenesis, thereby controlling tumor growth and invasion." (PMID 24349832, 2013). "FAK, pFAK and ILK analysis showed similar protein amounts in drug-resistant compared with drug-sensitive tumour cells." (PMID 22782340, 2012). "The question is therefore how increased ILK signalling in stromal cells can influence the aggressiveness of the tumour." (PMID 21426571, 2011). "ILK has been shown to have many roles in tumor development, with studies describing different effects in different tumors based on tissue origin." (PMID 22104495, 2011). "The overall ILK expression level was significantly higher in tumorous tissues (P = 0.004), with a significant stepwise increase in expression level along tumor progression from tumor stage I to IV (P = 0.045)." (PMID 21347395, 2011). "ILK contributes to tumour progression by increasing the expression of VEGF via the activation of PKB/Akt and HIF-1α, thereby stimulating angiogenesis." (PMID 21426571, 2011). "In this study, we elucidated the role of ILK in hepatocarcinogenesis by assessing its expression in human HCC tumor samples and functionally characterizing its role in HCC cell models." (PMID 21347395, 2011). "In line with this we correlated AR expression with the expression of ILK, p-Akt, E-cadherin, β-catenin in our sample as well as with tumor grade and TNM stage." (PMID 22191056, 2011). "ILK expression in either cirrhotic liver or stage I tumor was significantly lower than the advanced stage IV tumor." (PMID 21347395, 2011). "The resulting MMTV-Wnt/ILK mice were closely monitored for tumor development and growth, as well as for the tumor onset." (PMID 20565980, 2010). "This suggests a possible role for ILK in the background of MMTV-Wnt1 in expanding the luminal cell lineage with markedly enriched tumor-forming capacity." (PMID 20565980, 2010).
tumor (continued). "Other signaling molecules, such as P-ERK and fibronectin, also showed a marginal increase in the MMTV-Wnt/ILK tumor samples." (PMID 20565980, 2010). "A similar correlation also was reported in human colon cancer between ILK expression, activation of β-catenin, and tumor progression in vivo." (PMID 20565980, 2010). "Exogenous expression of a constitutively active form of ILK has been reported to enhance cellular radiosensitivity in a variety of human tumor cell models." (PMID 19649326, 2009). "Intriguingly, the same study also demonstrated a significant reduction of ILK expression with increasing tumor grade of human kidney cancers." (PMID 19649326, 2009). "A recent broad study using tissue microarray technique questioned these results by showing similar ILK expression in tumor tissue and normal tissue." (PMID 19649326, 2009). "In combination with radiotherapy, ILK mediates rigorous antisurvival effects in a variety of human tumor cell models and in mouse fibroblasts." (PMID 19649326, 2009). "They include carbohydratehomeostasis (PDK1), cell migration, proliferation and adhesions(ILK), signal transduction (ILK) and its modulation (14-3-3ε) and, finally, tumor suppression (PTEN)." (PMID 19096716, 2008). "In animal models ILK has been shown to have important activities in tumor growth/progression, angiogenesis, and tissue differentiation." (PMID 17563721, 2007). "Since our focus concerns oesophageal carcinoma, ILK expression is particularly intriguing since this tumour has a propensity to invade and metastasise." (PMID 16643659, 2006). "Tumor cells expressed ILK protein in most NSCLC cases, and strong expression was detected 31% (41 of 134) of the cases." (PMID 15631637, 2005). "In support of this and in conjunction with the known effects of ILK on Tcf-dependent gene transcription, dramatic shifts in the subcellular distribution of β-catenin were shown to occur at the leading edge of the tumour." (PMID 12771992, 2003). "The ILK signalling cascade seems to be involved in tumour growth, tumorigenesis and in the development of a metastatic phenotype." (PMID 12778079, 2003). "Compared to targets such as FAK and Src, which have been clinically tested in a wide range of tumours, ILK inhibitors are still in the laboratory or preclinical research stage, and there is a lack of data from large-scale clinical trials to fully assess their safety and efficacy." (PMID 40045379, 2025). "Therefore, the development of inhibitors targeting ILK, talin and cav-1 will provide new breakthroughs in the regulation of focal adhesion dynamics and related tumour therapies." (PMID 40045379, 2025). "Given the pronounced upregulation of ILK and other mTORC1-related genes in the food-insecure group, we conducted a more in-depth investigation into the mTORC1 pathway, aiming to elucidate its role in tumor adaptation to environmental stress." (PMID 40887471, 2025). "In addition to interactions with RTK, activation of the integrin signalling pathway in tumour cells also modulates the downstream effects of ILK." (PMID 40045379, 2025). "More direct evidence that ILK can modulate immune cell function and tumour progression comes from a study in which myeloid specific deletion of ILK reduced tumourigenesis in a spontaneous murine model of CRC which was associated with regulation of macrophage polarisation." (PMID 39641590, 2024). "Endothelin-1 is a well-known growth factor secreted by tumor cells, regulating cellular processes through signaling via mitogen-activated protein kinase (MAPK), protein kinase B (Akt), integrin-linked kinase (ILK), and proto-oncogene tyrosine-protein kinase Src pathways." (PMID 36542159, 2023). "Integrins facilitate cellular attachment to the ECM via the actin cytoskeleton and regulate focal adhesion kinase (FAK), integrin-linked kinase (ILK), and SRC kinase signaling pathways including Ras-ERK, PI3K/AKT, and YAP/TAZ, which support tumor growth and progression." (PMID 37958404, 2023).
tumor (continued). "Examination of human CRC tissue microarrays (TMAs), indicate that ILK+ myeloid cells (ILK+ CD11b+) are significantly elevated within the tumour compared to the adjacent normal tissues, suggesting a role of myeloid-ILK in human CRC development consistent with the results in the mouse models." (PMID 38077324, 2023). "Next, we examined whether the tumour-promoting M2 phenotypes are affected by deletion of ILK in macrophages." (PMID 38077324, 2023). "We found that CDKN2A and CMTM8 were tumor promoters, while ILK was tumor inhibitors." (PMID 35429970, 2022). "Therefore, ILK expression is negatively correlated with tumor purity in COAD, LUSC and STAD indicating an upregulation in the TME and positive correlation with immune cell infiltration levels." (PMID 35692780, 2022). "Furthermore, immunohistochemistry analysis confirmed that the nuclear expression of PCNA, a proliferative marker, was markedly reduced in these xenografic tumor-bearing ILK KO MKN1 cells." (PMID 35778385, 2022). "Moreover, ILK inhibition leads to suppression of tumor growth and inhibition of YAP activation in vivo." (PMID 35804980, 2022). "For instance, an inhibitor targeting the interaction interface of ILK:Parvin complex could be highly appreciated because IPP complex formation seems to be essential for the well-being of tumor cells." (PMID 35089438, 2022). "Notably, most of the research on the cellular cascades involving EMT triggered by ILK has been performed on transformed cells or tumor models." (PMID 36139812, 2022). "Since PD-L1 expression is involved in suppressing anti-tumor immune cell activity including NK cells, we examined whether ILK KD-mediated PD-L1 reduction in the CRC cells will display an effect in immune cell cytotoxicity." (PMID 35692780, 2022). "As a result, ILK could act as a tumor suppressor gene to affect the prognosis of tumors, which is consistent with our findings." (PMID 35429970, 2022). "Also, ILK expression is significantly higher in adjacent non-tumor tissues compared with primary tumors from the same patients." (PMID 35692780, 2022). "Moreover, the ability of ILK to promote tumor proliferation, invasion and metastasis has been widely studied." (PMID 35676936, 2022). "Although there was a correlation between ILK and immune cell infiltration, that does not mean ILK is implicated in anti-tumor immunity." (PMID 35692780, 2022). "In addition to its importance in the process of anoikis in tumor progression, several studies have provided new mechanistic insights as to the role of ILK in several steps of the metastatic cascade, including extravasation, colonization, and dormancy." (PMID 35804980, 2022). "Previous studies have shown that hypoxia or high HIF-1α expression could directly (ZEBI, Snail, Twist, CAV-1) or indirectly (Notch, TGF-β, integrin-linked kinase) regulate EMT and the migration and invasion of various tumour cells." (PMID 34631221, 2021). "Targeting ILK in solid tumors such as CRC could be effective in suppressing tumor growth via promoting TIS, enabling recruitment of anti-tumor immune cells into the TME thereby regulating SASP secretion." (PMID 34163519, 2021). "However, ILK also exhibits a scaffoldingprotein function inside cells, controlling cytoskeletal dynamics,and has been related to non-neoplastic diseases such as chronic kidneydisease (CKD)." (PMID 34790291, 2021). "ILK may also have a role in the expression of immune checkpoint, which is a barrier to anti-tumor immunity." (PMID 34163519, 2021). "We also examine how activating Toll-like receptors (TLRs) could trigger anti-tumor immune responses and be used as a combination therapy with ILK inhibition in CRC." (PMID 34163519, 2021).
tumor (continued). "The DNA component of NETs was found to act as a chemotactic factor to attract tumor cells through an extracellular DNA-sensor, CCDC25, expressed on tumor cells which subsequently activated the integrin-linked kinase (ILK)-β-parvin pathway to enhance cell motility." (PMID 34884995, 2021). "Moreover, the inactivation of ILK suppresses Yes-associated protein (YAP) activation and tumor growth in vivo, indicating that ILK plays a critical role in the suppression of the Hippo pathway in BC cells." (PMID 33043811, 2020). "Secondly, ILK forms a scaffold complex with some cytoskeleton proteins and plays a crucial role in regulating cell motility, cytoskeleton reorganization, focal adhesion, tumor progression and invasion." (PMID 31897228, 2020). "By inhibiting ILK, DZ-50 is then able to kill tumor cells via blocking AKT and FAK phosphorylation and subsequent cell survival, disrupting integrin adhesion (α5β1 and α2β1), and engaging ECM associated tumor suppressors." (PMID 32872127, 2020). "ILK knockdown resulted in slower tumor uptake and growth, confirming the observation made in vitro." (PMID 33256002, 2020). "Overall, the perturbations observed using Cpd22 indicate that ILK inhibition has the potential to be used as an adjuvant therapy especially in cases wherein the tumor location makes complete resection difficult as well as for cases of multiple incidences of recurrence." (PMID 32974197, 2020). "ILK attenuation via silencing or pharmaceutical inhibition, leads to apoptosis or inhibition of epithelial-to-mesenchymal transition, and cell invasion whereas ILK overexpression suppresses anoikis and promotes tumor growth and metastasis." (PMID 33043811, 2020). "Furthermore, antisense oligonucleotide silencing of ILK expression has been shown to suppress tumor growth in nude mice xenografts." (PMID 33256002, 2020). "Moreover, they showed that ILK was expressed in 20 normal breast tissue samples found adjacent to the tumor but it was significantly downregulated in the corresponding BC samples." (PMID 33043811, 2020). "Consistent with a tumor-promoting role of PINCH, it has been shown that PINCH interacts at focal adhesions sites with parvins, ILK, Nck1, Rsu-1, and several other partners to promote cell spreading, migration, and apoptosis resistance, features important for tumor cells." (PMID 29755929, 2018). "We thus examined whether GW501516 affect the phospho-AMPK and ILK levels in the C666-1 xenografts tumor samples." (PMID 30002625, 2018). "Finally, we found that ILK overexpression significantly enhanced growth, metastasis and angiogenesis of xenograft tumor; Whereas, RI has a contrary role compared to ILK in vivo and in vitro." (PMID 27576342, 2016). "Finally, the animal model experiment demonstrated that ILK significantly promoted growth and metastasis of transplanted tumor; tumors of EJ-ILK cell group were heavier and the microvascular density is higher than those in the control groups." (PMID 27576342, 2016). "In this study, ILK expression was shown to promote tumour progression." (PMID 26349061, 2015). "Moreover, ILK has been demonstrated to play important roles in tumor angiogenesis and radioresistance by upregulating HIF-1α-dependent expression of vascular endothelial growth factor (VEGF) and survivin, respectively." (PMID 25821081, 2015). "Both PINCH1 and ILK are upregulated in different tumor entities." (PMID 26460618, 2015). "Moreover, the ability of ILK to inhibit the expression of the tumor suppressor Foxo3a via YB-1-mediated transcriptional repression is noteworthy." (PMID 25821081, 2015). "While targeting of ILK results in radioresistance in head and neck and lung cancer cells and in radiosensitization of GBM cells, inhibition of PINCH1 causes radio- and chemosensitization in various tumor models." (PMID 26460618, 2015).
tumor (continued). "Tumor cell interactions with ECM molecules lead to clustering of integrins and activation of intracellular signaling pathways through the focal adhesion kinase (FAK), integrin-linked kinase (ILK) and Src kinase." (PMID 25594011, 2014). "More important, a stepwise increase in ILK expression was revealed along tumor progression." (PMID 21347395, 2011). "Nevertheless, a tumor suppressive role of ILK has been described in several tumors." (PMID 22191056, 2011). "In tumor tissue, ILK is observed to induce VEGF expression by Akt-mTOR dependent pathway." (PMID 21949693, 2011). "Therefore, based on the calliper measurement of individual tumors from each group, tumors from MMTV-Wnt/ILK mice showed a tumor-doubling time of 4 days, whereas the doubling time of the tumors in the MMTV-Wnt1 group was 3 times longer, averaging 12 days." (PMID 20565980, 2010). "To identify other possible signaling molecules and events involved in increased tumor incidence in MMTV-Wnt/ILK transgenic tumors, we performed global gene-expression analysis on RNA isolated from four independent tumors from each MMTV-Wnt1 and MMTV-Wnt/ILK transgenic model." (PMID 20565980, 2010). "Furthermore, mammary epithelial cells over-expressing ILK exhibit hyperplasia and tumor formation in vivo." (PMID 19409087, 2009). "In the future, small molecule antagonists of ILK may be used to interfere with recurrence in tumor patients." (PMID 15631637, 2005). "We also demonstrated that the expression of ILK correlated with tumor grade." (PMID 15631637, 2005). "Furthermore, increased ILK expression is correlated with progression of several tumor types, including prostate, gastric, and colon carcinomas." (PMID 15631637, 2005). "Since ILK has been reported to enhance tumour cell invasion, we postulated that ILK expression might be further dysregulated during the metastatic process." (PMID 12771992, 2003). "Additionally, diagnostic tools could be developed to profile the stromal cell populations and their ILK pathway activity within a patient's tumor." (PMID 41537745, 2026). "However, combined depletion of β1 and β4 significantly inhibited tumor growth, while simultaneous reduction of β4 and integrin‐linked protein kinase (ILK)—but not β1 and ILK—resulted in complete regression of primary tumor formation." (PMID 40327521, 2025). "Finally, contrary to our results, two immunohistochemical studies comparing tumor tissues with adjacent normal tissues of EC patients after resection demonstrated an overexpression of ILK in differentiated areas of tumor tissues as compared to adjacent normal tissues." (PMID 38727811, 2024). "CCDC25, upon sensing NET-DNA at AA21–25 on its extracellular domain, recruits integrin-linked kinase (ILK) via its intracellular C terminus and initiates the β-parvin-RAC1–CDC42 cascade to induce cytoskeleton rearrangement and directional migration of tumour cells." (PMID 36942262, 2023). "It should be noted that the majority of the research on the cellular cascades involving ILK has been performed on transformed or tumor cells, which might have its limitations in the extrapolation of these data on the ILK activity and function in nontransformed cells or organisms." (PMID 35089438, 2022). "Indeed, NETs can provide a physical shield that protects tumor cells from T and NK cell-mediated immune attack, or directly support tumor cell proliferation and invasiveness by activating the CCDC25-integrin linked kinase-β-parvin pathway or TGF-β signaling cascade." (PMID 35844591, 2022). "Here we substantiated that circ_0000515 expressions were exceptionally elevated in BC tissues and cell lines, and was interrelated with the tumor size and clinical stage of the sufferers, and circ_0000515 could promote the malign and biologic behaviors of BC cells via regulating miR-542-3p/ILK axis." (PMID 35029589, 2022). "Collectively, these data indicate that ILK could affect tumour growth by regulating angiogenesis." (PMID 33573141, 2021).